RPL23 (ribosomal protein L23)
Description:
Component of the large ribosomal subunit. The ribosome is a large ribonucleoprotein complex responsible for the synthesis of proteins in the cell.
Synonyms: rpL17; L23; uL14
Tractability: Small molecule: an approved drug acts on it; a structure with a bound ligand is known; a high-quality ligand is known. PROTAC: ubiquitination databases record sites on it; its protein half-life has been measured; a small molecule that binds it is known. Other modalities: a drug acting on it is in phase 2 or 3 trials.
Target class: Other cytosolic protein
Gene: Protein-coding gene on chromosome 17 (38,847,860 to 38,868,644, reverse strand). Ensembl gene ENSG00000125691.
Subcellular location: Cytoplasm
Subcellular location (Human Protein Atlas): Cytosol
Pathways (Reactome):
Metabolism of proteins: Eukaryotic Translation Termination; Formation of a pool of free 40S subunits; GTP hydrolysis and joining of the 60S ribosomal subunit; L13a-mediated translational silencing of Ceruloplasmin expression; PELO:HBS1L and ABCE1 dissociate a ribosome on a non-stop mRNA; Peptide chain elongation; Ribosome Quality Control (RQC) complex extracts and degrades nascent peptide; SRP-dependent cotranslational protein targeting to membrane; ZNF598 and the Ribosome-associated Quality Trigger (RQT) complex dissociate a ribosome stalled on a no-go mRNA
Metabolism of RNA: Major pathway of rRNA processing in the nucleolus and cytosol; Nonsense Mediated Decay (NMD) enhanced by the Exon Junction Complex (EJC); Nonsense Mediated Decay (NMD) independent of the Exon Junction Complex (EJC)
Cellular responses to stimuli: Response of EIF2AK4 (GCN2) to amino acid deficiency
Developmental Biology: Regulation of expression of SLITs and ROBOs
Disease: Viral mRNA Translation
Metabolism: Selenocysteine synthesis
Gene Ontology:
Molecular function: protein binding; RNA binding; structural constituent of ribosome; transcription coactivator binding; ubiquitin ligase inhibitor activity; ubiquitin protein ligase binding; large ribosomal subunit rRNA binding
Biological process: G1 to G0 transition; negative regulation of transcription by RNA polymerase II; negative regulation of ubiquitin-dependent protein catabolic process; positive regulation of cell population proliferation; protein stabilization; protein-DNA complex disassembly; regulation of G1 to G0 transition; cytoplasmic translation; negative regulation of myoblast fusion; ribosomal protein import into nucleus; spermatogenesis; striated muscle contraction; translation
Cellular component: cytoplasm; cytosol; cytosolic large ribosomal subunit; cytosolic ribosome; extracellular exosome; focal adhesion; membrane; nucleolus; nucleoplasm; protein-containing complex; ribosome; large ribosomal subunit; postsynaptic density; synapse
Genetic constraint (gnomAD): Loss-of-function variants: 0 observed, 17.18 expected, observed/expected ratio (o/e) 0, 90% interval 0 to 0.17. The upper end of that interval is the gene's LOEUF score, 0.17, which puts it in group 1 of 6, group 1 being the genes least tolerant of losing a copy. Missense variants: 76 observed, 178.72 expected, observed/expected ratio (o/e) 0.43, 90% interval 0.35 to 0.51. Synonymous variants: 60 observed, 66.31 expected, observed/expected ratio (o/e) 0.9, 90% interval 0.73 to 1.12.
Homologues: Orthologues: chimpanzee RPL23 (100% identical), guinea pig RPL23 (100% identical), macaque RPL23 (100% identical), mouse Rpl23 (100% identical), pig RPL23 (100% identical), rabbit RPL23 (100% identical), rat LOC134480573 (100% identical), tropical clawed frog rpl23 (100% identical), zebrafish rpl23 (99% identical), Drosophila melanogaster RpL23 (89% identical), Caenorhabditis elegans rpl-23 (86% identical).